RARA (retinoic acid receptor alpha)
Diseases named in the same sentence as RARA in open-access papers (continued):
Sharing a sentence is not in itself a finding about the gene and the disease.
tumor (continued). "These SEs are believed to drive the overexpression of RARA or IRF8 genes, leading to tumor development by targeting immature, undifferentiated, and proliferating cells." (PMID 40672386, 2025). "Our findings demonstrate upregulation of the NCoR1/RARα axis and elevated CMA activity in NCSLC tumor tissue and cell lines." (PMID 40490560, 2025). "In summary, our data revealed that WYC-209 showed an anti-tumor effect on GC both in vitro and in vivo by down-regulating the expression of WNT4 via RARα, making it a prospective strategy in antitumor therapy." (PMID 38178596, 2024). "As RARα (Retinoic Acid Receptor alpha) is one of the nuclear receptors mediating the transcriptomic effects exerted by ATRA, the retinoid represents the first example of targeted anti-tumor agent showing therapeutic efficacy." (PMID 38360674, 2024). "In terms of anti-tumor, compound 32 inhibited AML cell proliferation (IC50 = 1.6 ~ 16 μM), induce apoptosis and upregulate ASB2 and RARA, direct targets of FTO, to exert anti-tumor effects." (PMID 38711100, 2024). "It is possible that RARα and RARβ also play roles in WYC‐209‐induced tumor cell apoptosis and elucidation of their specific roles will require additional experiments." (PMID 36031407, 2022). "In particular, FTO suppressed the expression of tumor suppressors, including ankyrin repeat and SOCS box containing 2 (ASB2) and retinoic acid receptor alpha (RARA) by eliminating m6A sites." (PMID 35628623, 2022). "Among them, GATA1, RARA and LMO2 were lowly expressed, while E2F4 and CTBP2 were highly expressed in tumor parts." (PMID 35743687, 2022). "Although some studies focused on the effects of RARα and FSTL3 on tumor development, much less has been understood on RARα/FSTL3 axis regulation on tumor." (PMID 34858481, 2021). "Given that RARα is a transcription factor that participates in regulating transcription of various genes as well as miRNAs, we were thus inspired to investigate whether the anti-tumor efficacy of RARαS77A is attributed to activating transcription of functional miRNAs." (PMID 33902658, 2021). "Blocking PD-1/PD-L1 increased all-trans retinoic acid (ATRA) and type I IFN in the treatment-sensitive TME, which leads to activation of the retinoic acid receptor alpha (RAR-α) and subsequently CD38 expression on tumor cells." (PMID 32380703, 2020). "PML, originally identified to be involved in the rise of PML–RARα and RARα–PML fusion proteins, is a well-known tumor suppressor by regulating cell apoptosis and cell cycle." (PMID 31152142, 2019). "ATO induces autophagic cell death in several types of tumor cells, and degrades PML/RARα protein via mTOR pathway-mediated autophagy in APL cells." (PMID 29362482, 2018). "TGM2 was also reported to be upregulated in cancer cell lines by several important signaling pathways involved in tumor progression or metastasis, such as NFKB1/NF-κB, TGFB1/TGF-beta, RARA/RAR-alpha, and upon genotoxic stress." (PMID 26956429, 2016). "The most highly correlated gene was BRINP1 which has been shown to influence the rate of proliferation in tumour cell lines, in part by modulating the activities of the steroid and retinoic acid receptors ERA, AR and RARA." (PMID 26479384, 2015). "Here, subtype‐specific events involving either DNA copy number loss or CpG promoter methylation were found to involve TENC1, RARA, PCDHB11, PCDHB14, PCDHGA2 and PCDHGB2 indicative of candidate tumor suppressor genes in this context." (PMID 25468711, 2015). "In SKBR3 cells, simultaneous targeting of RARα with ATRA and HER2 with Lapatinib results in synergistic anti-tumor responses." (PMID 25961594, 2015). "The first evidence of the disruption of PML activity came from the study of PML-RARA in APL, where PML tumor suppressive functions are disrupted due to the fusion with the RARA." (PMID 23526763, 2013).
tumor (continued). "Another gene further upstream on chromosome 17, the retinoic acid receptor (RARA), was only found to be overexpressed in only some of the HER2+ tumour samples." (PMID 22067903, 2011). "Mechanistically, this BA enrichment drives tumor aerobic glycolysis and promotes immune evasion by modulating the interaction between the farnesoid X receptor (FXR) and retinoic acid receptor alpha (RARa)." (PMID 41958659, 2026). "Tumors grew in tumor‐naïve mice but did not grow (8/10 mice) or quickly regressed (2/10 mice) in previously tumor‐rejected RARα‐KO mice." (PMID 40068101, 2025). "Because of the differences in T cell infiltration in tumors of WT, RARα‐KO, and RARα‐TG mice, we examined the TCR clonotypes of tumor T cells by examining the sequences of complementarity‐determining region (CDR) 3 of TCR α and β chain at the single cell level." (PMID 40068101, 2025). "Overall, the negative effect of RARα on tumor growth was detected in the two types of tumors, but it was greater on MC38 than B16 tumors." (PMID 40068101, 2025). "Additionally, the green tea polyphenol epigallocatechin-3-gallate in combination with ATRA supports the degradation of the PML/RARα oncogene, restoring PML and inducing tumor promyelocyte differentiation." (PMID 40333775, 2025). "Notably, the CRC members identified include the retinoic acid receptor homologs RARA, RARB and the tumour suppressors HIC1 and SMAD3." (PMID 36147741, 2022). "Our results suggest that the inhibition of RARαS77 phosphorylation by either expressing RARαS77A or inhibiting RARα’s phosphokinase CDK7, can bypass RA stimuli to transactivate tumor-suppressive miR-3074-5p and reduce oncogenic DHRS3, thus overcoming the RA-resistance of TNBC." (PMID 33902658, 2021). "We show here that RARαS77 hyper-phosphorylation contributes to RA-resistance and tumor progression of TNBC by transcriptional suppression of miR-3074-5p, thus suggesting the RARα/miR-3074-5p/DHRS3 axis may serve as novel therapeutic targets for TNBC." (PMID 33902658, 2021). "Genes related to cancer pathways were downregulated upon atezolizumab treatment, including angiogenic factors for tumor vascularization (TNK1, AREG and KDR), proto-oncogenes (RET and MET) and tumor cell survival/migration/invasion (CDH1, RARA, WNK2, WNT4A, WNT9A, TGFB2, EGF, and LAMA3)." (PMID 32616706, 2020). "To evaluate whether S100A3/RARα interaction is a general phenomenon, we performed co-immunoprecipitation studies in ATRA-sensitive tumor cell lines of different origin." (PMID 30532072, 2019). "ATO can induce tumor cell differentiation, promote degradation of PML/RARα fusion protein, block specific intracellular signaling pathways, and trigger apoptosis by activating the intracellular caspase cascade, downregulating Bcl-2 expression and inhibiting NF-kB." (PMID 31632492, 2019). "The IHC results showed that RARα protein was strongly expressed in T tissues, presented dominantly in cytoplasm of tumor cells, but was weakly or not stained in P tissues." (PMID 28035062, 2017). "RA induces granulocytic differentiation by mediating gene transcription in various normal and tumor tissues, for example, transactivating RARγ to enhance HSC self‐renewal while promoting differentiation of committed myeloid progenitors by activating RARα." (PMID 27737899, 2016). "Interestingly, we found increased expression of RXR and RARA genes following Trastuzumab, Pertuzumab, and their combination treatment of the SKOV3 xenograft tumours." (PMID 27713148, 2016). "Although RARα is an important mediator of ATRA anti-tumor activity, it is unlikely to represent the only determinant of sensitivity." (PMID 25888236, 2015). "However, we recently observed that a synthetic RARα/β agonist, Am80, increased ACTH secretion by inducing transcription of pro-opiomelanocortin (Pomc) gene in murine pituitary corticotroph tumor AtT20 cells." (PMID 26714014, 2015).
tumor (continued). "RARα over-expression and knockdown experiments provide direct evidence for the involvement of the receptor not only in ATRA-dependent growth inhibition, but also in other aspects of ATRA anti-tumor activity." (PMID 25888236, 2015). "With IVA, there was four bone-related processes brought front only in the case of the tumour tissue—“myelopoiesis of bone marrow” (NPM1, RARA), “quantity of trabecular bone” (CREBBP, SMO), “outgrowth of bone marrow cells” (ALK) and “inflammatory response of bone marrow-derived macrophages” (RELA)." (PMID 25496518, 2014). "Modulation of the RARα/β to RARγ expression in mammary glands of normal mice, oncomice, and human mammary cell lines through the alteration of RAR-target gene expression affected cell proliferation, survival and tumor growth." (PMID 22920668, 2012). "The relative increase in RARγ isotype expression relative to the α and β isotypes correlates with tumor progression and lack of expression of RARα target genes involved in cell-cycle arrest and differentiation." (PMID 22920668, 2012). "The growth of tumour cells was also inhibited more than that of normal cells when RARβ together with RARγ, but not RARα alone, were antagonised." (PMID 15266311, 2004). "Additionally, analysis of gene expression in NSCLC cancer patients revealed a significant increase in both CMA score and NCoR1/RARα ratio in tumor tissue compared to non-tumorigenic lung tissue (Fig. EV7A,B)." (PMID 40490560, 2025). "In addition, silencing RARα inhibited the expression of PCNA, CyclinB1, CyclinD2, CyclinE, MMP9 and MDR1 and enhanced p21 expression, that may play critical roles in tumor growth, invasion, drug resistance." (PMID 28035062, 2017). "Interestingly, PU.1 interacts with both RARA and PML/RARA, and while PML/RARA has been demonstrated to downregulate PU.1, ATRA treatment restores PU.1 levels, thus suggesting a tumor suppressive role of PU.1 in APL, through the transcriptional regulation of specific downstream target genes." (PMID 27626703, 2016). "When RARA transcriptional activity is functionally inhibited, physiological RA activation of growth-promoting signaling pathways, like PI3K/AKT, is no longer counteracted by transcriptional RARA activation of tumor suppressor signaling pathways like the TGFB-TGFBR2 signaling pathway." (PMID 27894085, 2016). "Taking our results together with those of previous studies, we supposed that TRIM24 may function as a tumor suppressor in ESCC independent of RARα-dependent transcription." (PMID 27689360, 2016). "We next asked whether the ability of C16 in combination with a RARα agonist to induce differentiation of TNBC cells, to block tumorsphere formation, and to inhibit mammary ductal tree hyperplasia, will translate into anti-tumor and anti-metastatic effect and will increase survival." (PMID 27286261, 2016). "Therefore, RARβ could act as tumor suppressor even in the absence of ATRA, and RARβ loss expression gives AP-1 over-expression, which could abrogate the growth-inhibitory effects of ATRA through RARα and RARγ, resulting in retinoid resistance." (PMID 32012980, 2020). "In a panel of 39 NSCLC tumor tissues and 10 non-tumorigenic lung tissues from human patients, we found significantly higher levels of NCoR1 nuclear protein levels in NSCLC tumors, while nuclear protein levels of RARα were comparable between the two groups." (PMID 40490560, 2025). "The leukemic cells of the other six PML::RARA-negative AML cases with APL-like morphological features, except the KMT2A-positive patient (due to the specific tumor biology), had more or less a typical myeloid immunophenotype, with strong expression of pan-myeloid antigens (CD33, CD13, MPO)." (PMID 36980947, 2023). "However, to date, this NCoR1/RARα-dependent regulation of CMA has not been established in cancer cells, nor has it been determined whether it can impact tumor growth." (PMID 40490560, 2025).
cancer (139 papers, 1999 to 2026). A tumor composed of atypical neoplastic, often pleomorphic cells that invade other tissues. "Our analysis of publicly available data, revealed that the expression of RARA, the gene coding RARα, is inversely associated with cancer patient survival." (PMID 40068101, 2025). "Factors that negatively affect the RARA transcriptional function are expected to predispose mammary epithelial cells to physiological RA cancer-promoting effects." (PMID 27894085, 2016). "Rearrangement of TBL1XR1 (3q26.32) have been identified in various cancers involving different genes, including RARA (17q21), HMGA1 (6p21), TP63 (3q28), RET (10q11.2), and PIK3CA (3q26.32)." (PMID 41123735, 2025). "SEs play key roles in maintaining cancer cell identity and promoting oncogenic transcription, our group had reported that inhibition of SEs-related proteins RARα and CDK7 exerts anti-TNBC effects." (PMID 41173847, 2025). "Ligands for PPARƔ, AR, PR and RARα activate p21 expression in cancer cells through interactions of NR/Sp1 or NR/Sp4 with two or more members of the Sp1–6 binding sites in the proximal region of the p21 gene promoters." (PMID 39858066, 2025). "Neddylation of the RARα moiety in PML/RARα induces aberrant phase separation in cancer cells and enhances RARα DNA‐binding ability, which hinders the normal phase separation of this PML moiety." (PMID 40599234, 2025). "In non-cancer cells, RARα/Sp1 enhances induction pyruvate dehydrogenase kinase 4 (PDK4), guanylyl cyclase/atrial natriuretic peptide receptor-A (Npr1), apelin and TNFα-inducible protein 3-interacting protein 1 (TNIP1)." (PMID 39858066, 2025). "Additional evaluation of data generated by the TCGA Research Network revealed an overall increase in the NCoR1/RARα ratio correlating to increasing CMA score between cancer types." (PMID 40490560, 2025). "In cancer cells, RARα/RXRα (NR1B1/NR2B1) interacts with Sp1 and Sp3 on the 17β-hydroxysteroid dehydrogenase type 2 (HSD17B2) promoter, and retinoic acid (RA) induces its expression." (PMID 39858066, 2025). "In sum, T cell‐expressed RARα is identified as a novel negative regulator and potential target of intervention in promoting anti‐cancer T cell immunity." (PMID 40068101, 2025). "To examine this in our cancer models, we compared the expression of RARα, RARβ, RARγ, RXRα, RXRβ and RXRγ in AB1-HA tumors, which are sensitive to combination tretinoin–CY therapy, and AE17, CT26 and WEHI164 tumors, which are resistant." (PMID 38350880, 2024). "Because of the significance of iron and oxidative stress in ferroptosis initiation, it is important to investigate the unclear connection between RARA and ferroptosis to enhance the role of this vital TF in cancer therapy." (PMID 38902322, 2024). "The selected pG4-BS include sequences from various gene segments of cancer-associated genes, such as EZR, PRN1, RARA and NF1." (PMID 37094040, 2023). "The initial evidence revealing the association between SUMOylation and cancer derived from the identification of the promyelocytic leukemia protein (PML) and the oncogenic fusion protein PML—retinoic acid receptor-α (RARα) as SUMO substrates." (PMID 37686409, 2023). "There is a knowledge gap that currently exists as to how the RAR subtype-selective retinoids like the RARγ agonist IRX4647 or the RARα antagonist IRX6696 affect cancer immunity." (PMID 37689790, 2023). "RARβ mRNA was either undetectable or present at low basal levels while RARα and RARγ mRNAs were each expressed at readily detectable basal levels in these examined cancer cell lines." (PMID 37689790, 2023). "ATRA’s success has deepened our understanding of the role of the RARα pathway in normal hematopoiesis and leukemogenesis, and it has influenced a generation of cancer drug development." (PMID 37509198, 2023). "On the contrary, RARA was highly expressed in 6/33 cancers and lowly expressed in 5/33, demonstrating the controversial expression pattern." (PMID 34489925, 2021).
cancer (continued). "Regarding specific cancer-associated genes, the CYT-high subgroup had more CNAs, including gains in NF1, CDK12, ERBB2, RARA, MDM4 and MYC; and losses in BRCA1, CD274 and APC." (PMID 34316699, 2021). "In the mouse testicular embryonal carcinoma cell line, RA induces Bmp2 while simultaneously repressing Bmp4, specifically through RARα and RARγ." (PMID 34292881, 2021). "Nearly all receptors binding p85αPI3K can cooperate with cAMP-PKA signals via phosphorylation of p85αPI3KSer83: ERα and retinoic acid receptor-alpha (RARα) have been extensively studied for their association with PI3K and their involvement in cancer risk." (PMID 32684934, 2020). "In vitro pharmacological RA treatment of T47D cells was shown to induce either an anticancer or cancer-promoting action, depending on the functional status of RARA." (PMID 32823855, 2020). "RARA, SRC and SMO can also potentially be used as diagnostic, prognostic and/or therapy-response biomarkers in cancer." (PMID 32099096, 2020). "Arsenic causes cancer cell apoptosis by binding to protein kinase M2 (PKM2), located on the surface of PML/RARA." (PMID 29206204, 2017). "Another chimeric transcript up regulated in our cancer samples is a fusion of the transcriptional regulator-encoding gene, RARA (retinoic acid receptor, alpha), with the 3′ UTR from the PSME3 (proteasome activator subunit 3) gene." (PMID 28851357, 2017). "According to literature, in cancer cells RA can activate PI3K kinase by enhancing RARA physical interaction with the PI3K catalytic subunit (p110)." (PMID 27894085, 2016). "There are three distinct isoforms RAR (α, -β and -γ), among which RARα is known to play a pivotal role in the control of cellular differentiation and apoptosis, and is therefore an important drug target for cancer therapy and prevention." (PMID 28035983, 2016). "Pharmacologic activation of RARα, or inhibition of RARγ activity, reduces cancer cell growth in vitro, thereby suggesting that a specific RARα agonist would be a more effective method of cancer treatment than an RAR pan-agonist such us ATRA." (PMID 22920668, 2012). "Several studies demonstrated that RARα mediates the differentiation of some types of cancer cell lines." (PMID 22087283, 2011). "Based on the increased epithelial cellularity of the KO-glands and published data implicating RARα in anti-cancer activity, we expected that the RARα1/KO mice crossed with the MMTV-wnt1 mice will be more susceptible to wnt1-induced tumorigenesis." (PMID 20923554, 2010). "Among the five investigated nuclear retinoid receptors, only expression of RARα mRNA was significantly decreased in intestinal metaplasia, dysplasia and cancer tissues when compared to adjacent normal tissues." (PMID 10389997, 1999). "Expression of RARα and RARβ were found in three and seven cancer tissues, respectively, and levels of RXRα mRNA were significantly decreased in poorly differentiated cancer tissues." (PMID 10389997, 1999). "Expression of RARα, RARβ, RARγ, RXRα and RXRβ was found in most cell types in gastric mucosa tissues from normal individuals as well as in distal normal tissues from cancer patients." (PMID 10389997, 1999). "This prompted us to investigate whether cancer cells may also use the RARα/NCoR1 axis to sustain their elevated CMA activity." (PMID 40490560, 2025). "Additionally, both RARA and VDR are classified as nuclear receptors that have been linked to cancer." (PMID 40334012, 2025). "Additionally, ATRA has known off-target transcription-independent effects on ERK and PI3k-Akt signaling pathways in NSCLC that counteract RARα-mediated inhibition of cancer cells growth and make ATRA a poor candidate compound for NSCLC treatment." (PMID 40490560, 2025).